ALB (albumin)
Diseases named in the same sentence as ALB in open-access papers (continued):
Sharing a sentence is not in itself a finding about the gene and the disease.
dengue (continued). "In addition, testing for infecting serotype and monitoring platelet count and serum albumin, AST, and ALT concentrations during the febrile phase of illness could improve the early prediction of severe dengue." (PMID 33640077, 2021). "On D0, median plasma concentrations of fibrinogen and albumin as well as WBC absolute and neutrophils relative counts were decreased, whereas concentration of TAT, DD, AST, ALT, vWF and sST2 were elevated in the dengue group before defervescence compared to the OFI group." (PMID 32544159, 2020). "Most laboratory results among patients with severe and non-severe dengue were similar with the exceptions of platelet counts and albumin, which were both significantly lower among patients with severe dengue compared to those with non-severe dengue (p < 0.001)." (PMID 26468084, 2015). "Thus, we investigated the associations of NAFLD with liver transaminase level, platelet count, degree of hemoconcentration, albumin level and length of hospital stay (LOS) in dengue-infected patients with and without plasma leakage." (PMID 30332476, 2018).
Alzheimer disease (70 papers, 2008 to 2025). A progressive, neurodegenerative disease characterized by loss of function and death of nerve cells in several areas of the brain leading to loss of cognitive function such as memory and language. "It is known that there is a strong association between DKK1, albumin and AD since a significantly decreased level of albumin is associated with over-expression of DKK in Alzheimer’ disease." (PMID 36291101, 2022). "Midlife elevated plasma levels of systemic inflammatory markers such as fibrinogen and albumin are correlated with reduced brain volumes in brain areas associated with dementia such as Alzheimer’s disease (AD) in later life." (PMID 30524237, 2018). "Albumin has been implicated in Alzheimer's disease (AD) because it can specifically bind to and transport amyloid beta (Aβ), the causative agent of AD, under physiological conditions." (PMID 18665237, 2008). "Albumin has been implicated in Alzheimer's disease (AD) since it can bind to and transport amyloid beta (Aβ), the causative agent of AD; albumin is also a potent inhibitor of Aβ polymerization." (PMID 18665237, 2008). "In addition, related KEGG pathways Alzheimer’s disease and neurodegeneration are specifically associated with albumin." (PMID 39021677, 2024). "Serum albumin becomes insoluble and aggregates during co–incubation with methylglyoxal, glycolaldehyde and ribose–modified albumin, thereby forming amyloid–like aggregates that induce cytotoxicity, which is linked to the development of Alzheimer’s disease." (PMID 37007029, 2023). "The present study indicated increased levels of antibodies recognizing egg albumin in the serum and CSF of a great percentage of patients with AD, which correlates immune response to egg albumin with Alzheimer’s Disease." (PMID 40867530, 2025). "The results indicated an increased concentration of antibodies against native and denatured egg albumin in the CSF of the majority of patients with severe Alzheimer’s Disease with a low presence in the CSF of patients with mild and moderate disease." (PMID 40867530, 2025). "According to the results, increased antibodies against egg albumin were observed in the CSF of a great proportion of patients with severe Alzheimer’s Disease." (PMID 40867530, 2025). "In a study involving 101 Alzheimer’s disease (AD) patients and 101 healthy controls, the AD group exhibited significant decreases in albumin, bilirubin, and uric acid levels." (PMID 39114530, 2024). "It has been reported that the redox state of albumin in CSF differs from that in serum and that in Alzheimer’s disease (AD), CSF albumin is significantly shifted to the oxidized state." (PMID 36555448, 2022). "This study was designed to detect structural and functional brain changes in Alzheimer’s disease (AD) patients treated with therapeutic plasma exchange (PE) with albumin replacement, as part of the recent AMBAR phase 2b/3 clinical trial." (PMID 35867135, 2022). "We believe that young and undamaged albumin would significantly improve the cognitive ability of patients with Alzheimer’s disease." (PMID 34439857, 2021). "The affinity between Albumin and Aβ has given rise to AMBAR (Alzheimer’s Disease Management by Albumin Replacement) project for steps towards AD treatments." (PMID 34825129, 2021). "The use of TPE, where the patient’s plasma is filtered and replaced with a 5–20% albumin solution, was investigated for its effectiveness to mitigate the progression of mild-to-moderate Alzheimer’s disease." (PMID 33191466, 2021). "The unexpected powers of “young plasma” to counter-act the deterioration of the ageing brain and serum albumin's therapeutic efficacy in the treatment of Alzheimer's disease have been highlighted recently." (PMID 30266430, 2019).
Alzheimer disease (continued). "In line with our findings, a previous study found that subjects with Alzheimer's disease and elevated CSF/serum albumin ratio (a proxy for BCB impairment) had significantly higher mean plasma triglycerides and lower mean HDL cholesterol than individuals without BCB impairment." (PMID 40529789, 2025). "Albumin is able to bind to the precursor agent of the AD, amyloid-beta (Aβ) in the blood, preventing its deposition in the brain and potentially slowing the pathological progression of Alzheimer’s disease." (PMID 41346383, 2025). "Therefore, from a perspective of Alzheimer’s disease prevention, clinicians should exercise greater vigilance to avoid a decrease in serum albumin levels, even within clinically normal ranges." (PMID 39114530, 2024). "A study found that low serum albumin may increase amyloid accumulation in patients with Alzheimer’s Disease." (PMID 38398429, 2024). "Albumin plays a role in preventing excessive oxidative stress induced by inflammation in aging neuronal cells, and inflammatory mechanisms are involved in the pathogenesis of Alzheimer’s disease." (PMID 35160273, 2022). "Furthermore, five proteins (IGHV3.9, PRG4, VWF, ALB and CST3) were significantly associated with ESR values, with CST3, a protein active in neurodegenerative (Alzheimer’s Disease) and demyelinating (multiple sclerosis) neurological conditions." (PMID 35033099, 2022). "An excess of dimeric and oligomeric forms of albumin may be the first symptom of neoplastic or neurodegenerative diseases (e.g., Alzheimer’s disease)." (PMID 35897662, 2022). "Ahn, Sung-Min and his colleagues found evidence in a pilot phase study of the Human Brain Proteome Project that microglial cells in the brain may synthesize albumin and these cells may play a beneficial role in Alzheimer’s disease by secreting albumin." (PMID 30430305, 2018). "Similarly, the CDD can predict five proved metabolic factors (acetoacetate, glucose, albumin, free cholesterol, and fatty acid length) for the Alzheimer's disease, and the Mendelian randomization can only predict one proved risk factor (Esterified cholesterol) for the Alzheimer's disease." (PMID 39440482, 2024). "Based on results demonstrated in Alzheimer’s disease, we theorized that PE with albumin replacement (PE-A) might alter the metabolic profile of plasma and cerebrospinal fluid in patients with amyotrophic lateral sclerosis (ALS) by removing disease-inducing molecules." (PMID 34791571, 2022). "As investigated in Alzheimer’s disease, PE with albumin replacement (PE-A) may alter the metabolic profile of the plasma and cerebrospinal fluid in ALS patients by removing disease-inducing molecules and providing benefits related to the multiple functions of albumin." (PMID 34791571, 2022). "Finally, AGE-albumin could be an excellent biomarker as a therapeutic target for neurodegenerative diseases including Alzheimer’s disease." (PMID 22662249, 2012). "Human serum albumin (HSA) is a natural depot of amyloid-β peptide (Aβ), a key player in Alzheimer’s disease (AD)." (PMID 40149967, 2025). "AD, Alzheimer’s disease; LBD, Lewy body dementia; MMSE, Mini-Mental State Examination; CSFP, cerebrospinal fluid pressure; Qalb, cerebrospinal fluid (CSF)/serum albumin ratio; SBP: systolic pressure (before lumbar puncture)." (PMID 38243235, 2024). "The AMBAR (Alzheimer Management By Albumin Replacement) study (EudraCT# 2011‐001598‐25; ClinicalTrials.gov ID: NCT01561053) used a therapeutic approach for Alzheimer's disease (AD) based on plasma exchange (PE) with albumin replacement (PE‐Alb)." (PMID 39476248, 2024). "For instance, ultrasound, especially FUS, have a place in the symptomatic treatment of Alzheimer's disease, transiently opening the BBB to allow an unexpected entry of immunoglobulins and albumin." (PMID 34335175, 2021).
Alzheimer disease (continued). "Prevention of amyloid β peptide (Aβ) deposition via facilitation of Aβ binding to its natural depot, human serum albumin (HSA), is a promising approach to preclude Alzheimer’s disease (AD) onset and progression." (PMID 34072751, 2021). "Decreased Fpn expression and abnormal iron deposition significantly increased NOX4, 4-HNE, and MDA levels in damaged astrocytes of cerebral cortex, and five hub genes (JUN, SLC2A1, TFRC, ALB, and NFE2L2) closely related to ferroptosis were identified in Alzheimer's disease (AD) patients." (PMID 36062196, 2022). "We investigated whether CSF concentrations of neurofilament light chain (NFL), soluble amyloid-β protein precursor α (sAβPPα), sAβPPβ, and CSF/serum albumin ratio could separate SSVD from healthy controls, Alzheimer’s disease (AD), and mixed dementia (combined AD and SSVD)." (PMID 37980667, 2023). "Grifols' recent Alzheimer Management by Albumin Replacement (“AMBAR”) study investigated the effects of plasmapheresis with albumin replacement, plus intravenous immunoglobulin (IVIG) in some subjects, in patients with mild-to-moderate Alzheimer's disease (AD)." (PMID 32547478, 2020).
colon carcinoma (70 papers, 2009 to 2026). "Radical surgery is safe and feasible for patients over 80 years of age with colon cancer, and preoperative albumin<35 g/L and right colon cancer are independent risk factors for the development of severe postoperative complications after surgery." (PMID 38577607, 2024). "The results of the multivariate analysis in this study showed that preoperative albumin <35 g/L was an independent risk factor for severe complications after radical surgery in elderly colon cancer patients (OR=2.45, 95% CI: 1.10-5.87, P=0.041)." (PMID 38577607, 2024). "A major difference was observed for albumin levels, showing that the nutritional balance for colon cancer in association with type two diabetes is fragile (average albumin 28.3 g/L in diabetic patients vs. 36.6 g/L in the non-diabetic group) (p = 0.00023)." (PMID 37627906, 2023). "For instance, anti-cancer drugs were loaded into mannosylated bovine serum albumin (BSA) NPs to target drug-resistant colon cancer cells and tumor-associated macrophages, which both highly express mannose receptors and SPARC." (PMID 31858848, 2020). "In the right-sided colon tumour subgroup, only the albumin-NLR was associated with OS (p = 0.048), with the survival curves being well separated." (PMID 30419863, 2018). "The present study describes the synthesis and use of NIR fluorescent albumin nanoparticles as a diagnostic tool for detection of colon cancer." (PMID 22891637, 2012). "Therefore, it is believed that albumin is closely related to the development of gastrointestinal cancer and many studies focused on its association with risks of gastrointestinal cancer, especially colon cancer." (PMID 34041866, 2021). "This neutrophil-hitchhiking albumin nanoplatform provides a targeted and biocompatible strategy for effective colon cancer therapy." (PMID 41590804, 2026). "When NMI was administered to a mouse model of colon cancer, both albumin and MAOA were detected by mass spectrometry within the fluorescent ~ 65 kD band of tumor lysate." (PMID 39904854, 2025). "As previously demonstrated in the literature, having low albumin levels before colon cancer surgery increases morbidity and reduces overall survival." (PMID 38230385, 2024). "The aim of this prospective study was to evaluate the prognostic significance of the C reactive protein-to-albumin ratio (CAR) in patients with colon cancer." (PMID 39064483, 2024). "Recent evidence has confirmed that lower serum albumin levels predict higher mortality rates, particularly regarding prognosis among cancer patients, such as colon cancer." (PMID 37580693, 2023). "In the present work, we evaluate, for the first time, the prognostic value of the recently developed HALP (hemoglobin, albumin, lymphocyte, and platelet) index in Hispanic colon cancer patients." (PMID 36467502, 2022). "The results indicate that PIC-loaded albumin NPs are more effective against the invasion of colon cancer cells (CaCo-2, and HT29 cells) due to their enhanced and targeted activity." (PMID 31906321, 2020). "The preparation of albumin-bound fluorophore nanoparticles has been successfully used for intraoperative NIR-II fluorescence imaging of orthotopic mouse colon tumor and metastatic lesions with dimensions as small as 0.5 mm × 0.3 mm." (PMID 31101816, 2019). "The addition of 10% foetal bovine serum (FBS) or 1% bovine serum albumin accordingly inhibited CoPP‐induced apoptosis and HO‐1 protein expression in human colon cancer cells." (PMID 31199053, 2019). "For the left-sided colon cancer subgroup, the time-dependent ROC curve of the albumin-NLR was also superior to that of the SIS and mGPS." (PMID 30419863, 2018).
colon carcinoma (continued). "Our recent study proved that loading of the oxidized form of DDC (disulfiram) into albumin-coated chitosan NPs masked toxicity of disulfiram to normal colon cells and increased its selectivity towards colon cancer cells." (PMID 29545617, 2018). "Taking colon cancer into consideration, some studies which reported predictability of survival using pre-operative albumin levels in serum, reported variable cut off values of albumin as a predictor of survival." (PMID 23590192, 2013). "This study developed albumin nanoparticles loaded with 6-shogaol (NPs/6-shogaol) and utilized activated neutrophils as carriers to transport the nanoparticles across vascular barriers for colon cancer therapy." (PMID 41590804, 2026). "C reactive protein and albumin serum levels are very accessible and cost-effective biomarkers, which may have prognostic utility for colon cancer patients." (PMID 39064483, 2024). "In the MC38 murine colon carcinoma model, three studies investigated the use of a peptide vaccine, targeting a previously identified neoepitope in the Adpgk protein, delivered via synthetic nanoparticles or albumin/albumin-binding vaccine (AlbiVax) complexes." (PMID 33033852, 2021). "Nevertheless, there were also two studies reporting nonsignificant associations between albumin and colon cancer risk." (PMID 34041866, 2021). "A nested case‐control study showed that the risk of colon cancer increased from the highest to the lowest quartiles of serum albumin (ptrend = 0.05) whereas no statistically significant dose‐response trend was observed for bilirubin or uric acid." (PMID 34041866, 2021). "Therefore, albumin nanoparticles have high efficiency against the migration of cancer cells to prevent the metastasis of colon cancer cells." (PMID 31906321, 2020). "Herein, an endogenous hydrogen sulfide (H2S) accelerated Fe(III)/Fe(II) transformation and photothermal synergistically enhanced CDT strategy based on ellagic acid-Fe-bovine serum albumin (EA-Fe@BSA) nanoparticles (NPs) was developed for colon tumor inhibition." (PMID 32226542, 2020). "A low serum albumin of 29 g l−1 was found, as expected in locally advanced colon cancer." (PMID 30931133, 2018). "Thus, we aimed to further evaluate the in vivo effects of albumin-conjugated androgens in colon cancer animal models." (PMID 19948074, 2009). "In addition, to the best of our knowledge, the C reactive protein-to-albumin ratio as a prognostic factor for colon cancer has previously been studied exclusively in Asian countries on a more heterogenous population, which included both colon and rectal cancer." (PMID 39064483, 2024). "Further studies in a colon cancer mouse model found the ~ 65 kD SDS-PAGE band, bound to NMI, contained both MAOA and albumin proteins by mass spectrometry." (PMID 39904854, 2025). "Our study showed that colon cancer patients with low NLR, high ALB and high CHOL had a more favorable survival compared to those with high NLR, low ALB and low CHOL." (PMID 39351349, 2024). "It has been observed that albumin, when administered as fusion protein ALB-IL2, demonstrates a T cell-mediated anticancer effect in colon tumors." (PMID 38732562, 2024). "The components of the bedside leak score (i.e., the preoperative albumin and the CRP on POD1 and POD3) are commonly used blood parameters in patient care after colon cancer surgeries." (PMID 37601530, 2023). "They introduced Raman-labeled hollow Ag–Au nanoshells, which were protected by a bovine serum albumin (BSA) layer, for the purpose of detecting and performing PTT on colon cancer." (PMID 37920521, 2023). "Colon cancer patients with high serum CRP and those with low albumin levels were significant more likely to suffer SSI occurrence (CRP: P < 0.05; Albumin: P < 0.01)." (PMID 31906993, 2020). "Different opinions exist on the relationship between the C-reactive protein-to-albumin ratio (CAR) and the prognosis of colon cancer." (PMID 33299880, 2020).